ADAM10 (ADAM metallopeptidase domain 10)
Description:
Transmembrane metalloprotease which mediates the ectodomain shedding of a myriad of transmembrane proteins, including adhesion proteins, growth factor precursors and cytokines being essential for development and tissue homeostasis. Associates with six members of the tetraspanin superfamily TspanC8 which regulate its exit from the endoplasmic reticulum and its substrate selectivity. Cleaves the membrane-bound precursor of TNF at '76-Ala-|-Val-77' to its mature soluble form. Responsible for the proteolytical release of soluble JAM3 from endothelial cells surface. Responsible for the proteolytic release of several other cell-surface proteins, including heparin-binding epidermal growth-like factor, ephrin-A2, CD44, CDH2 and for constitutive and regulated alpha-secretase cleavage of amyloid precursor protein (APP). Contributes to the normal cleavage of the cellular prion protein. Involved in the cleavage of the adhesion molecule L1 at the cell surface and in released membrane vesicles, suggesting a vesicle-based protease activity. Also controls the proteolytic processing of Notch and mediates lateral inhibition during neurogenesis (By similarity). Required for the development of type 1 transitional B cells into marginal zone B cells, probably by cleaving Notch (By similarity). Responsible for the FasL ectodomain shedding and for the generation of the remnant ADAM10-processed FasL (FasL APL) transmembrane form. Also cleaves the ectodomain of the integral membrane proteins CORIN and ITM2B. Mediates the proteolytic cleavage of LAG3, leading to release the secreted form of LAG3 (By similarity). Mediates the proteolytic cleavage of IL6R and IL11RA, leading to the release of secreted forms of IL6R and IL11RA. Enhances the cleavage of CHL1 by BACE1 (By similarity). Cleaves NRCAM (By similarity). Cleaves TREM2, resulting in shedding of the TREM2 ectodomain. Involved in the development and maturation of glomerular and coronary vasculature (By similarity). During development of the cochlear organ of Corti, promotes pillar cell separation by forming a ternary complex with CADH1 and EPHA4 and cleaving CADH1 at adherens junctions (By similarity). May regulate the EFNA5-EPHA3 signaling. Regulates leukocyte transmigration as a sheddase for the adherens junction protein VE-cadherin/CDH5 in endothelial cells. (Microbial infection) Promotes the cytotoxic activity of S.aureus hly by binding to the toxin at zonula adherens and promoting formation of toxin pores.
Synonyms: CD156c; KUZ; MADM; HsT18717; AD10; AD18; CDw156; RAK
Tractability: Small molecule: a structure with a bound ligand is known; a high-quality ligand is known; it belongs to a druggable protein family. Antibody: UniProt places it where antibodies can reach, with high confidence; its Gene Ontology location is reachable by antibodies, with high confidence; UniProt predicts a signal peptide or a membrane-spanning region; the Human Protein Atlas places it where antibodies can reach. PROTAC: ubiquitination databases record sites on it; its protein half-life has been measured; a small molecule that binds it is known.
Target class: Metallo protease MAM clan; Metallo protease; Protease; Enzyme; Metallo protease M12B subfamily
Chemical probes: CHEMBL253665, GI254023X
Gene: Protein-coding gene on chromosome 15 (58,588,809 to 58,749,842, reverse strand). Ensembl gene ENSG00000137845.
Subcellular location: Cell membrane; Golgi apparatus membrane; Cytoplasmic vesicle, clathrin-coated vesicle; Cell projection, axon; Cell projection, dendrite; Cell junction, adherens junction; Cytoplasm
Subcellular location (Human Protein Atlas): Plasma membrane; Vesicles
Pathways (Reactome):
Signal Transduction: Activated NOTCH1 Transmits Signal to the Nucleus; NOTCH2 Activation and Transmission of Signal to the Nucleus; NOTCH3 Activation and Transmission of Signal to the Nucleus; NOTCH4 Activation and Transmission of Signal to the Nucleus; Signaling by EGFR
Disease: Constitutive Signaling by NOTCH1 HD Domain Mutants; Constitutive Signaling by NOTCH1 HD+PEST Domain Mutants; Constitutive Signaling by NOTCH1 PEST Domain Mutants; Constitutive Signaling by NOTCH1 t(7;9)(NOTCH1:M1580_K2555) Translocation Mutant
Metabolism of proteins: Amyloid fiber formation; Post-translational protein phosphorylation; Regulation of Insulin-like Growth Factor (IGF) transport and uptake by Insulin-like Growth Factor Binding Proteins (IGFBPs)
Extracellular matrix organization: Collagen degradation; Degradation of the extracellular matrix
Developmental Biology: EPH-ephrin mediated repulsion of cells
Immune System: Neutrophil degranulation
Gene Ontology:
Molecular function: endopeptidase activity; metalloendopeptidase activity; metallopeptidase activity; protein binding; protein homodimerization activity; integrin binding; metalloendopeptidase activity involved in amyloid precursor protein catabolic process; metallodipeptidase activity
Biological process: amyloid precursor protein catabolic process; constitutive protein ectodomain proteolysis; membrane protein ectodomain proteolysis; monocyte activation; negative regulation of amyloid precursor protein biosynthetic process; negative regulation of amyloid-beta formation; negative regulation of cell adhesion; negative regulation of gene expression; pore complex assembly; positive regulation of cell growth; positive regulation of cell migration; positive regulation of cell population proliferation; positive regulation of T cell chemotaxis; positive regulation of tumor necrosis factor production; positive regulation of tumor necrosis factor-mediated signaling pathway; response to tumor necrosis factor; cell-cell signaling; extracellular matrix disassembly; in utero embryonic development; integrin-mediated signaling pathway; Notch signaling pathway; protein processing; adherens junction organization; cochlea development; epidermal growth factor receptor ligand maturation; and 8 more
Cellular component: cell surface; cytoplasm; extracellular exosome; focal adhesion; Golgi apparatus; Golgi membrane; Golgi-associated vesicle; membrane; perinuclear endoplasmic reticulum; plasma membrane; pore complex; synaptic membrane; tetraspanin-enriched microdomain; endoplasmic reticulum lumen; specific granule membrane; tertiary granule membrane; adherens junction; axon; clathrin-coated vesicle; dendrite; glutamatergic synapse; postsynaptic density
Genetic constraint (gnomAD): Loss-of-function variants: 15 observed, 83.79 expected, observed/expected ratio (o/e) 0.18, 90% interval 0.12 to 0.28. The upper end of that interval is the gene's LOEUF score, 0.28, which puts it in group 1 of 6, group 1 being the genes least tolerant of losing a copy. Missense variants: 595 observed, 920.88 expected, observed/expected ratio (o/e) 0.65, 90% interval 0.6 to 0.69. Synonymous variants: 303 observed, 305.51 expected, observed/expected ratio (o/e) 0.99, 90% interval 0.9 to 1.09.
Homologues: Orthologues: chimpanzee ADAM10 (100% identical), rabbit ADAM10 (98% identical), macaque ADAM10 (98% identical), dog ADAM10 (97% identical), mouse Adam10 (96% identical), pig ADAM10 (96% identical), rat Adam10 (90% identical), guinea pig ADAM10 (87% identical), tropical clawed frog adam10 (82% identical), zebrafish adam10a (76% identical), zebrafish adam10b (58% identical), Drosophila melanogaster kuz (45% identical), and 4 more. Paralogues in human: ADAM17 (24% identical), ADAM9 (22% identical), ADAM12 (22% identical), ADAM19 (22% identical), ADAM15 (22% identical), ADAM33 (22% identical), ADAM8 (21% identical), ADAM22 (20% identical), ADAM28 (20% identical), ADAM11 (19% identical), ADAM20 (19% identical), ADAM29 (19% identical), and 8 more.
Diseases named in the same sentence as ADAM10 in open-access papers:
ADAM10 is named in the same sentence as 269 diseases in open-access papers, as found by Europe PMC text mining. Sharing a sentence is not in itself a finding about the gene and the disease. The quoted sentences say what the papers report.
Alzheimer disease (107 papers, 2007 to 2026). A progressive, neurodegenerative disease characterized by loss of function and death of nerve cells in several areas of the brain leading to loss of cognitive function such as memory and language. "SHMT2 has been implicated in Alzheimer's disease (AD) pathology through its role in enhancing ADAM10 translation via interaction with the 5' untranslated region of ADAM10 mRNA." (PMID 40738465, 2025). "ADAM10 has been linked to Alzheimer’s disease due to its cleavage of the amyloid precursor (AP) protein, which generates an α-fragment and prevents the generation and aggregation of APβ fragments, thus limiting disease progression." (PMID 39497138, 2024). "The dysregulation of ADAM10 expression and function has been implicated in pathological conditions, including Alzheimer’s disease (AD)." (PMID 36674432, 2023). "In another study, the mutation of ADAM‐10 which causes loss‐of‐function can be a predisposing factor for the development of Alzheimer disease." (PMID 36946281, 2023). "Triggering receptor expressed on myeloid cells 2 (TREM2) is cleaved by ADAM10 at the H157-S158 bond, and the H157Y variant found in an Alzheimer disease patient increased its cleavage and caused a loss-of-function phenotype." (PMID 32873342, 2020). "Adam10 is abundantly expressed in the brain and is linked to epilepsy, Alzheimer’s disease, Hunting’s disease, and developmental disorder Fragile X syndrome because of its role in regulating the activity of excitatory synapses." (PMID 31791390, 2019). "A rare H157Y variant of TREM2 is associated with increased risk of Alzheimer’s disease; amino acid 157 is at the cleavage site for ADAM10, and H157Y is shed more readily." (PMID 30013551, 2018). "Alzheimer's disease (AD) is associated with reduced levels of ADAM10 in the human brain while ADAM10 over-expression has been shown to improve cognitive function in mouse models of AD." (PMID 28437250, 2017). "Previous evidence has indicated that downregulated ADAM10 gives rise to epileptic seizures in Alzheimer’s disease, and this study investigated the association of ADAM10 with temporal lobe epilepsy (TLE) from a genetic perspective." (PMID 27445971, 2016). "As a result ADAM10 has been implicated as a potential target of modulation in diseases ranging from Alzheimer disease to heart disease and thrombosis to inflammation and cancer." (PMID 26668317, 2016). "ADAM10 is associated with Alzheimer’s disease (AD) and is a potential therapeutic target." (PMID 36668668, 2023). "On top of its potential as a possible therapeutic target, the circulating level of ADAM10 and/or its substrates may be useful as a diagnostic as well as prognostic biomarker for cardiovascular disease, Alzheimer disease, and cancer." (PMID 35705192, 2022). "As a type 1 transmembrane protein, a disintegrin and metalloprotease 10 (ADAM10) is responsible for the cleavage of a variety of cell surface molecules and has been implicated in the pathogenesis of Alzheimer disease, atherosclerosis, and inflammatory and neoplastic disorders." (PMID 35705192, 2022). "As ADAM10 is implicated in several diseases, including Alzheimer’s dementia, cardiovascular diseases, and inflammation, including inflammation of the adipose tissue, it is possible that the reprogramming of TSPAN14 plays a role in cardio-metabolic health by regulating ADAM10 function." (PMID 35740266, 2022). "While Alzheimer disease (AD) is associated with reduced ADAM10 levels, thereby resulting in excess amyloidogenic processing of amyloid precursor protein, ADAM10 is hyperactive in the HD brain at both pre- and postsynaptic localizations." (PMID 34211373, 2021). "Finally, mutations in ADAM10 increase β-amyloid production and mitochondrial impairment associated with Alzheimer’s disease pathogenesis." (PMID 33686350, 2021).
Alzheimer disease (continued). "On microglia, increased ADAM10 cleavage of a rare variant of the scavenger receptor triggering receptor expressed on myeloid cells 2 may increase susceptibility to Alzheimer’s disease." (PMID 30013551, 2018). "Moreover, two rare missense mutations in ADAM10 (Q170H and R181G) result in the increased accumulation of beta-amyloids related to Alzheimer’s disease due to disruption of the prodomain chaperone." (PMID 27218255, 2016). "Another major substrate of ADAM10 is the amyloid precursor protein (APP) for which ADAM10 acts as the constitutive alpha-secretase and thus possesses the ability to prevent the generation of the pathogenic Aβ peptide in Alzheimer’s disease (AD)." (PMID 26802628, 2016). "ADAM10 is the dominant α-secretase in the brain and recently two rare mutations in ADAM10 were identified which were suggested as predisposing for late-onset Alzheimer's disease." (PMID 25748120, 2015). "Finally, ADAM10 has been implicated in the pathogenesis of Alzheimer's disease (AD): ADAM10 possesses alpha-secretase activity, involved in the alternate amyloid precursor protein processing pathway to the beta-secretase pathway that produces amyloid beta." (PMID 26793057, 2015). "In other tissues, ADAM-10 is associated with aberrant cadherin processing, which is thought to cause downstream functional alterations in cell-cell adhesion and β-catenin signaling in the pathogenesis of disease states such as cancer and Alzheimer disease." (PMID 21197111, 2010). "On APP, ADAM10 activity causes the generation of a C-terminal membrane-anchored fragment and a neuroprotective soluble ectodomain (sAPPα), precluding amyloid-β (Aβ) formation and their aggregation leading to amyloid plaque load that is a hallmark of Alzheimer’s disease (AD)." (PMID 36674432, 2023). "In contrast, promotion of ADAM10 activity on neurons could alleviate Alzheimer disease by preventing the generation of pathogenic β-amyloid peptides, and on platelets could prevent heart attack and stroke caused by thrombosis, through collagen receptor GPVI shedding." (PMID 26668317, 2016). "Several compounds modulating the expression and activity of ADAM10 have been investigated for their therapeutic potential in clinical trials, including the use of Rapamycin for the inhibition of ADAM10 activity in Alzheimer disease." (PMID 38399697, 2024). "ADAM10 cleaves amyloid precursor protein (APP) to contribute to the pathophysiology of Alzheimer’s disease." (PMID 39211038, 2024). "Increased expression in Alzheimer’s disease.Exerts a negative regulatory effect on ADAM10 and is triggered by Aβ." (PMID 38883980, 2024). "miR-221 was downregulated in the blood of patients with Alzheimer’s disease (AD), and it acted as a negative regulator of ADAM10." (PMID 38338859, 2024). "Here we present a new enzymatic approach for the potential treatment of Alzheimer's disease using a soluble form of ADAM10." (PMID 37266401, 2023). "In our study, we focused on an estrogen receptor that is known to be affecting Alzheimer’s disease—α-secretase, specifically ADAM10." (PMID 35401074, 2022). "This has led to the idea of increasing, or at least restoring ADAM10 activity, as a therapeutic option for Alzheimer’s disease." (PMID 36533182, 2022). "The role of certain ADAM10 substrates in disease progression suggests that ADAM10 is a promising therapeutic target, with notable possibilities for Alzheimer’s disease, cancer, and inflammatory diseases." (PMID 34201472, 2021). "The ADAM metallopeptidase domain 10 (ADAM10) gene was already identified as a biomarker for Alzheimer’s disease in humans, with functions related to the cleavage amyloid precursors that act during the inflammation process of senile plaques." (PMID 35052358, 2021). "Multiple reviews have been published supporting the potential of ADAM10 protein in platelets and cerebrospinal fluid to serve as a biomarker for Alzheimer's disease diagnoses." (PMID 32265938, 2020).
Alzheimer disease (continued). "Primarily, we found several aging (klotho, major vault 1, gelsolin, huntingtin, and fragile X mental retardation protein) and Alzheimer’s disease (ADAM10, apoE receptor, ChAT, APP, and PSEN1; most of these are also involved in aging) related sequences." (PMID 32449011, 2020). "SIRT1 suppresses β-amyloid production by activating the α-secretase gene ADAM10 and induces Notch signaling pathway, illustrating its potential in the treatment of Alzheimer’s disease." (PMID 32089065, 2020). "Dysregulated ADAM10 activity is assumed to play a central role in diverse pathologies including Alzheimer’s disease, allergic responses, and cancer development." (PMID 30753537, 2019). "While the function of miRNA-1306 has been seldom reported, studies have strongly suggested that miRNA-1306 can target and inhibit ADAM10 gene, a key gene of Alzheimer’s disease (AD)." (PMID 30935128, 2019). "ADAM10 overexpression in Alzheimer’s disease mouse model prevents formation of amyloid plaques and is a therapeutic target for Alzheimer’s disease." (PMID 31396262, 2019). "The metalloprotease ADAM10 is a drug target in Alzheimer's disease, where it cleaves the amyloid precursor protein (APP) and lowers amyloid‐beta." (PMID 30833305, 2019). "A disintegrin and metalloproteinase 10 (ADAM10) is a synaptic enzyme that has been previously shown to limit amyloid-β1–42 (Aβ1–42) peptide formation in Alzheimer’s disease (AD)." (PMID 30989630, 2019). "Adam10 was initially identified as an alpha-secretase in the processing of the amyloid precursor protein, which is involved in Alzheimer’s disease." (PMID 30075790, 2018). "For example, we found Alzheimer’s Disease risk genes APOE, PLD3, TREM2, UNC5C, AKAP9, and ADAM10 in our orthologous gene list." (PMID 30382841, 2018). "Studies have demonstrated the beneficial role of ADAM10 in reducing the pathologic damage of Alzheimer’s disease (AD)." (PMID 29843688, 2018). "ADAM10 has been implicated in myriad immune diseases including T-cell acute lymphoblastic leukemia (T-ALL), asthma, atherosclerosis, and Alzheimer’s disease." (PMID 30013551, 2018). "Given that increased ADAM10 activity protects the brain from β-amyloid deposition, this strategy is viable in terms of treating neurodegenerative conditions, including Alzheimer’s disease (AD)." (PMID 29382156, 2018). "Upregulation of ADAM10 precludes the generation of neurotoxic β-amyloid protein (Aβ) and represents a plausible therapeutic strategy for Alzheimer’s disease (AD)." (PMID 29942252, 2018). "Crucially, we also show that the Alzheimer's disease‐associated H157Y TREM2 variant was shed more rapidly than wild type from HEK293 cells, possibly by a novel, batimastat‐ and ADAM10‐siRNA‐independent, sheddase activity." (PMID 28855301, 2017). "ADAM10 is an important modulator of amyloid beta protein production, accumulation of which is central to the pathologies of Alzheimer's disease and cerebral amyloid angiopathy." (PMID 28437250, 2017). "Overexpression of ADAM10 was also effective in animal mouse models of Alzheimer's disease (AD) and reduced plaque load as well as deficits in learning and memory." (PMID 28367112, 2017). "Both ADAM10 and ADAM17 have been implicated in the development of neurodegenerative diseases such as Alzheimer’s disease." (PMID 27549131, 2016). "One of the proteases is the a-disintegrin-and-metalloprotease 10 (ADAM10) which acts as alpha-secretase of the Alzheimer's disease amyloid precursor protein." (PMID 26802628, 2016). "There has been a lot of interest in finding drugs that activate ADAM10 to treat Alzheimer’s disease." (PMID 26802628, 2016). "Overall the experiments proved that ADAM10 is important not only for the prevention of Alzheimer’s disease, but also for the normal development of the brain." (PMID 26802628, 2016). "For example, by inhibiting the ADAM10 metalloprotease, Sfrp1 has been considered to play an important role in pathological events of Alzheimer's disease." (PMID 26943045, 2016).